SMAD2 (SMAD family member 2)
Diseases named in the same sentence as SMAD2 in open-access papers (continued):
Sharing a sentence is not in itself a finding about the gene and the disease.
atherosclerosis (continued). "As a result, we could conclude that therapy with EVs transfected or not with Smad2/3 siRNA reduced the inflammatory condition, thus helping to regress the atherosclerosis-associated dysfunction already installed." (PMID 35478972, 2022). "Also, the potential of using a targeted therapy based on Smad2/3 siRNA to block Smad2/3, pivotal downstream effectors in development of atheroma function, could protect against atherosclerosis development." (PMID 35478972, 2022). "Mechanistically, the miR-375-3p/STX6 signaling axis promoted endothelial cell senescence via the SMAD2/p15 pathway in a SMAD2-dependent manner, and overexpression of STX6 attenuated atherosclerosis progression in mice." (PMID 41367311, 2025). "Inhibition of FXa/FIIa can downregulate the activation of the Smad2/3 signaling pathway and MMP2 expression mediated by protease-activated receptor 2 (PAR2) to limit the severity of aortic aneurysm and atherosclerosis." (PMID 35637715, 2022). "This discrepancy is likely indicative of the multifactorial nature of atherosclerosis, and the observation that Smad2/3 does not necessarily exert a dominant influence across all phases or states of the disease." (PMID 41154653, 2025). "For this purpose, an animal model of atherosclerosis, hypertensive–hyperlipidemic (HH) hamster, was transplanted with EVs (ADSCs) or EVs (MSCs) transfected or not with Smad2/3 siRNA." (PMID 35478972, 2022). "Importantly, the investigation of clinical plasma samples from patients with atherosclerosis showed the up‐regulation of SNHG16 and Smad2, and down‐regulation of miR‐205." (PMID 31441592, 2019). "In conclusion, adropin can reduce atherosclerosis in ApoE-/-/Enho-/- mice through non-lipid-regulating pathway, by inhibiting EndMT via the TGF-β/Smad2/3 signaling pathway." (PMID 37903785, 2023).
bladder cancer (22 papers, 2012 to 2025). "The presence of SMAD2 C-terminal mutations caused an 80% reduction in overall tumour growth formation thus underscoring the role for TGFβ signalling in bladder cancer tumourigenesis." (PMID 31554791, 2019). "In this study, the associations between GP73/TGF‐β1/Smad2 and the clinic pathological features of patients with bladder cancer were explored." (PMID 29349903, 2018). "Furthermore, GP73, TGF‐β1 and Smad2 were highly expressed in bladder cancer and were associated with clinical features such as the clinical and pathological stages and LNMs of bladder cancer." (PMID 29349903, 2018). "Interestingly, most (up to 86%) of TGF-β1 secreted by bladder cancer cells is encapsulated in exosomes that target healthy fibroblasts and stimulate their differentiation into cancer-associated fibroblasts (CAFs) by triggering SMAD2 phosphorylation." (PMID 31842336, 2019). "Together, those data indicated that TRIM9/CEACAM6 mediated Smad2/3 signaling activation to modulate bladder cancer progression." (PMID 37249822, 2023). "Previous publications have reported that PPM1A modulates TGF-β signaling by dephosphorylating and inactivating SMAD2 in epithelial cell, keratinocyte, and bladder cancer cells." (PMID 36752205, 2023). "Some previous researchers have elaborated on the connection between GOLM1 and the TGF-β1/Smad2 signaling pathway in bladder cancer and HCC." (PMID 36499755, 2022). "Our findings indicated that TGF-β signaling induced EMT in GCB-resistant bladder cancer cells by activating Smad2/3, thereby upregulating Slug and ZEB2 and ultimately reducing hENT1 and hCNT1, the major influx transporters of GCB." (PMID 33922395, 2021). "The overexpression of hepaCAM prevented the translocation of p-SMAD2/3 from the cytoplasm to the nucleus in bladder cancer cells." (PMID 35174173, 2021). "Our results indicate that the TGFβ-Smad2/3 signaling pathway-induced EMT process is involved in GCB resistance in bladder cancer by transactivating Slug and ZEB2 and downregulating hCNT1 and hENT1." (PMID 33922395, 2021). "A recent study has found that phosphorylated Smad2/3proteins are overexpressed in bladder carcinoma compared to adjacent normal tissue." (PMID 31238579, 2019). "PPM1A down-regulation increased epithelial-to-mesenchymal transition (EMT) progress and invasion through increasing the activity of Smad2/3 signaling pathway in bladder cancer." (PMID 29898761, 2018). "Moreover, the combination of Smad2/3 signaling inhibitor and chemotherapeutic agents effectively improved the treatment outcome of bladder cancer in vivo." (PMID 37249822, 2023). "Moreover, blockade of Smad2/3 signaling increased chemo-sensitivity to MMC and GEM in TRIM9 overexpressed cells, indicating that TRIM9 upregulated Smad2/3 to facilitate bladder cancer development and chemoresistance." (PMID 37249822, 2023). "The TGF-β/Smad2/3 signaling pathway was suppressed by silencing Trim59 in bladder cancer." (PMID 35458126, 2022). "The expression levels of GP73, TGF‐β1 and Smad2 in bladder cancer tissue samples were significantly higher than those in adjacent and normal bladder tissue samples (61.8% versus 10.8% versus 3.8%, 72.5% versus 19.6% versus 7.5% and 65.7% versus 15.7% versus 6.6%, respectively) (all P < 0.05)." (PMID 29349903, 2018). "In addition, TGF-β induced MMPs expression has been shown to enhance the invasion and migration capabilities of various cancer cells, and our study also identified an increased MMP2 expression in the CEACAM6/Smad2/3 signaling medicated bladder cancer progression." (PMID 37249822, 2023). "Thus, the TRIM9/Smad2/3 signaling might represent promising prognostic markers and therapeutic targets for bladder cancer." (PMID 37249822, 2023). "Herba Patriniae, the third herbal component of YYFZBJS, has demonstrated anti-tumor effects in colorectal and bladder cancers through the P5330, TGF-β-Smad2/3-E-cadherin 5, and MAPK signaling pathways 31, supporting its role as a tumor suppressor." (PMID 40302810, 2025).
bladder cancer (continued). "Exosomes derived from high-grade bladder cancer cells increased the viability, migration, invasion, and clonogenicity of low-grade bladder cancer cells and activated major EMT signaling pathways, including the β-catenin, Notch, and Smad2/3 signaling pathways." (PMID 38473285, 2024). "In summary, our experiments suggest that TRIM9 plays an oncogenic role in bladder cancer progression by increasing cell proliferation, migration, and inducing chemoresistance via CEACAM6/Smad2/3 signaling pathway." (PMID 37249822, 2023). "Secondly, our exploration about effects of TRIM9 on cell biological processes showed that TRIM9 promoted bladder cancer proliferation, migration and chemoresistance via CEACAM6/Smad2/3 signaling." (PMID 37249822, 2023). "Highly malignant bladder cancer cells transmit LINC00960 and LINC02470 to early bladder cancer cells through exosomes, thereby inducing further deterioration and activating the EMT process by upregulating the β-catenin, Notch, and Smad2/3 signaling pathways." (PMID 35359397, 2022). "High expression of Smad2 and Smad4 in the TGF-β signaling pathway predicts longer OS in bladder cancer patients, while TGF-β1 is inversely correlated with the survival rate." (PMID 34141706, 2021). "the combination therapy of TGF-β compared with TGF, 1 + hepaCAM significantly down-regulated p-SMAD2/3, procaspase 3/8/9 and PARP, and induced bladder cancer cell apoptosis-β alone." (PMID 35174173, 2021). "Moreover, in bladder cancer, nucleolar and spindle associated protein 1 (NUSAP1) was upregulated, and its expression was closely related to the poor prognosis of patients, which was also demonstrated to regulate EMT via the TGF-β signaling pathway, as well as p-Smad2/3 and vimentin expression." (PMID 32456355, 2020). "The TGF-β1/SMAD2 pathway is also utilized by Golgi membrane protein 73 (GP73) to induce EMT and promote invasion and metastasis of bladder cancer." (PMID 31842336, 2019). "Specifically, TGF-β1 activates SMAD2, which triggers mTORC2 activation, resulting in AKT phosphorylation and stimulation of the motility of bladder cancer cells." (PMID 31842336, 2019). "Specifically, S1P1 triggers phosphorylation of SMAD2/3, which activates the TGF-β signaling pathway and production of TGF-β by bladder cancer cells." (PMID 31842336, 2019). "In summary, our results provide evidence that GP73 can activate the TGF‐β1/Smad2 signalling pathway and induce the EMT via down‐regulating WT1 expression, thereby promoting the invasion and metastasis of bladder cancer." (PMID 29349903, 2018). "This study investigated the effects of Golgi membrane protein 73 (GP73) on the epithelial–mesenchymal transition (EMT) and on bladder cancer cell invasion and metastasis through the TGF‐β1/Smad2 signalling pathway." (PMID 29349903, 2018). "We found that the protein level of MMP9 was unchanged, while TRIM9 overexpression facilitated MMP2 production in Biu-87/T24 cells, and blockade of Smad2/3 signaling suppressed MMP2 expression, indicating that Smad2/3 mediated downstream MMP2 production in bladder cancer cells." (PMID 37249822, 2023). "Our findings indicate that exosome-derived LINC00960 and LINC02470 from high-grade bladder cancer cells promote the malignant behaviors of recipient low-grade bladder cancer cells and induce EMT by upregulating β-catenin signaling, Notch signaling, and Smad2/3 signaling." (PMID 32517366, 2020). "Nevertheless, the activity of the GP73/TGF‐β1/Smad2 pathway in the regulation of the EMT in bladder cancer has not been studied." (PMID 29349903, 2018). "Therefore, the aim of this study was to investigate how GP73/TGF‐β1/Smad2 regulates the EMT and promotes the invasion and metastasis of bladder cancer." (PMID 29349903, 2018).
bladder cancer (continued). "Exosomes derived from high-grade bladder cancer cells enhanced the viability, migration, invasion and clonogenicity of recipient low-grade bladder cancer cells and activated major EMT-upstream signaling pathways, including β-catenin signaling, Notch signaling, and Smad2/3 signaling pathways." (PMID 32517366, 2020). "It is well known that TGF-β/Activin/Nodal signaling is transduced by SMAD2 and SMAD3, and increased TGF-β1 level can revert a malignant phenotype to a less aggressive phenotype in rat bladder carcinoma cell line lacking TGF-β1." (PMID 23251617, 2012).
lung adenocarcinoma (22 papers, 2015 to 2026). A carcinoma that arises from the lung and is characterized by the presence of malignant glandular epithelial cells. "Overexpression of miR-136 results in the inhibition of metastasis-associated traits in lung adenocarcinoma cells via Smad2 and Smad3." (PMID 31195953, 2019). "Metformin, an AMPK activator, inhibits the TGF-β-induced increase in Smad2 and Smad3 phosphorylation in A549 lung adenocarcinoma cells." (PMID 41392217, 2025). "Although ARE-Lux with FoxH1 co-expression is often used as a Smad2-specific reporter based on the activity observed in Smad2−/− mouse embryonic fibroblasts, it is activated by TGF-β in SMAD2 knockout A549 human lung adenocarcinoma cells." (PMID 38569937, 2024). "MDM2 has been documented to activate the Smad2 /3 signaling pathway to promote the EMT of lung adenocarcinoma cells." (PMID 32423468, 2020). "TCM significantly promoted FUT4/LeY expression and Smad2/3 phosphorylation in lung adenocarcinoma cell lines (A549 and H1299) in a dose-dependent manner." (PMID 28423676, 2017). "Mouse embryonic fibroblast (MEF) of AIMP1-knockout mice reportedly exhibit increased phosphorylation of Smad2 and Smad3, and knockdown of AIMP1 using short-interfering RNA (siRNA) promotes phosphorylation of Smad2 in human lung adenocarcinoma A549 cells." (PMID 26890138, 2016). "MiR-155-5p suppresses the migration and invasion of lung adenocarcinoma cells by targeting Smad2." (PMID 36232331, 2022). "On the basis of these findings, we concluded that M2 macrophages could promote FUT4/LeY expression in lung adenocarcinoma cells through the TGF-β1/Smad2/3 signaling pathway." (PMID 28423676, 2017). "In conclusion, we provide insight into the biological function of AK2 in human lung adenocarcinoma and demonstrate that AK2 overexpression activates the TGF-β/Smad3/Smad2/Smad4 signaling pathway, leading to enhanced invasion via EMT." (PMID 34630090, 2021). "MiR-769-5p was found upregulated in hypoxia-induced human lung adenocarcinoma cells, affecting the cell cycle of A549 cells, while its predicted target genes, including ARID1A and SMAD2, were downregulated." (PMID 33329055, 2020). "In lung adenocarcinoma cells, MTF inhibited TGFB1-induced phosphorylation of SMAD family member 2/3 (Smad2/3) dose-dependently by using the LKB1/AMPK axis." (PMID 30241339, 2018). "Furthermore, conditioned medium from irradiated and untreated CAFs was applied to A549 lung adenocarcinoma tumor cells to explore activation of STAT-1 and Smad2/3-dependent pathways via secretion of IFNs and TGF-β from CAFs respectively." (PMID 39308864, 2024). "Cao and colleagues found that UPF1 may inhibit TGF-β signaling by decreased expression of Smad2/3, MIXL1 and SOX17 in lung adenocarcinoma." (PMID 34922601, 2021). "Moreover, our study found that silencing of DANCR reduced the protein levels of Smad2/3, which might be regulated by MDM2, since MDM2 has been documented to promote Smad2/3 activation in lung adenocarcinoma." (PMID 32423468, 2020).
osteoarthritis (22 papers, 2015 to 2025). A noninflammatory degenerative joint disease occurring chiefly in older persons, characterized by degeneration of the articular cartilage, hypertrophy of bone at the margins and changes in the synovial membrane. "On the other hand, it is responsible for inhibiting chondrocyte proliferation in osteoarthritis by suppressing the transcriptional regulator Mothers against decapentaplegic homolog 2 (SMAD2)." (PMID 39967042, 2025). "The downregulation of miR‐29a/b/c expression in chondrocytes by TGF‐β1 ligands and phosphorylated Smad2/3 suggests its role in the pathogenesis of osteoarthritis." (PMID 38957040, 2024). "Two mouse models of osteoarthritis (OA) were used to examine protein expressions of Tgf-β1 and p-Smad2/3 in condylar cartilages at early degenerative stages." (PMID 28542404, 2017). "In addition to the three miRNAs identified in our study, recent research has expanded our understanding of miRNAs in osteoarthritis (OA), highlighting their significant involvement in key OA-associated signaling pathways, including MMP13, STAT3, SMAD2/3, NOTCH3/Notch, and NF-κB." (PMID 39796139, 2024). "Moreover, recent studies have further revealed the extensive roles of miRNAs in osteoarthritis, particularly in crucial pathways such as MMP13, STAT3, SMAD2/3, NOTCH3/Notch, and NF-κB signaling." (PMID 39796139, 2024). "TGF-β signaling is crucial for modulating osteoarthritis (OA), and protein phosphatase magnesium–dependent 1A (PPM1A) has been reported as a phosphatase of SMAD2 and regulates TGF-β signaling, while the role of PPM1A in cartilage homeostasis and OA development remains largely unexplored." (PMID 36752205, 2023). "Additionally, studies have reported that TGF-β signaling mediated by Smad2/3 may be involved in OA progression by inducing the recruitment of MSCs and osteoprogenitors to the subchondral bone, ending with aberrant bone remodeling that initiates and worsens osteoarthritis." (PMID 36017131, 2022). "Furthermore, in studies on osteoarthritis, an age-related shift in the ALK1/ALK5 ratio altered TGF-β downstream signals by favoring Smad1/5/8 over Smad2/3." (PMID 31658594, 2019). "In addition, the TGF-β/Smad2/3 pathway plays an important role in cartilage degeneration, maintenance of cartilage and the ECM, and inhibition of the progression of osteoarthritis." (PMID 38609995, 2024). "In osteoarthritis, the material properties of the cartilage ECM deteriorate as chondrocytes inappropriately shift the balance from canonical (Alk5/Smad2/3) to non-canonical (Alk1/Smad1/5/8) TβRI signaling." (PMID 26652004, 2015).
Hyperglycemia (18 papers, 2016 to 2026). An increased concentration of glucose in the blood. "The present work shows that hyperglycemia in human macrophages changes the balance between Smad1/5 and Smad2/3-dependent signaling." (PMID 39062148, 2024). "We found that the combination of nicotine and hyperglycemia increased the activation of Smad2/3 and the expression of its target genes Id1 and Id4 but decreased the activation of Smad1/5/8 and the expression of its target gene Snail." (PMID 37415117, 2023). "Western blotting and IHC staining showed that the combination of nicotine and hyperglycemia significantly increased the activation of Smad2/3 and decreased the activation of Smad1/5/8 compared with nicotine or hyperglycemia alone." (PMID 37415117, 2023). "We found that TGF-β1/SMAD2/3 signaling mediates the stimulatory effect of hyperglycemia on DDR2 that in turn enhances collagen type 1 expression via ERK1/2 MAPK activation." (PMID 31805124, 2019). "In our in vitro experiment, hyperglycemia increased the phosphorylation of Smad2/3, while neferine reversed this effect." (PMID 27533252, 2016). "In agreement with earlier literature, persistent hyperglycemia stimulated canonical TGF-β signaling, as evidenced by increased TGF-β and phosphorylated Smad2/3 in the kidneys of the DN group." (PMID 37237918, 2023). "Metformin was found to attenuate hyperglycaemia-induced increase in DDR2 mRNA and protein expression by inhibiting TGF-β1/SMAD2/3 signalling that mediates the stimulatory effect of hyperglycaemia on DDR2 expression." (PMID 36614028, 2022). "We demonstrate for the first time that metformin prevents hyperglycaemia-induced increase in DDR2 expression in vascular adventitial fibroblasts by inhibiting the TGF-β1/SMAD2/3 signalling pathway, which enhances DDR2 expression in response to hyperglycaemia." (PMID 36614028, 2022). "Further, in isolated rat vascular adventitial fibroblasts and VSMCs, hyperglycemia increased DDR2 and collagen type I expression via TGF-β1/SMAD2/3, which was attenuated by resveratrol." (PMID 31805124, 2019). "In this study, our results demonstrated that liraglutide inhibits HG-induced Smad2 phosphorylation and EndMT via the AMPK pathway, suggesting that liraglutide mediates preservation of the endothelial phenotype and prevents hyperglycaemia-induced EndMT." (PMID 31207939, 2019). "In addition, liraglutide prevents hyperglycemia-induced Smad2 phosphorylation and EndMT via the AMPK pathway, indicating the prevention of liraglutide towards hyperglycemia-induced EndMT." (PMID 38645427, 2024). "We demonstrated that PTβR2I binds with TβR2 and differentially regulates TGFβ1 pathways: PTβR2I downregulates the TGFβ1/p38 pathway while not affecting the TGFβ1/Smad-2/3 pathway under the hyperglycemia environment in diabetic wounds." (PMID 37422462, 2023). "Our results revealed that the expression levels of TGF-β, phosphorylated-Smad2 (p-Smad2) and phosphorylated-Smad3 (p-Smad3) were decreased with ENO1 knockdown, whereas the total Smad2 and Smad3 expression levels were not significantly different between the normal glucose and hyperglycemia groups." (PMID 31889896, 2019).